GCG (glucagon)
Diseases named in the same sentence as GCG in open-access papers (continued):
Sharing a sentence is not in itself a finding about the gene and the disease.
Hypoglycemia (continued). "Due to their glucose-dependent mechanisms of insulin secretion augmentation and glucagon suppression, GLP-1 RAs are able to effectively improve glycemic control in T2DM patients without substantially increasing the risk of hypoglycemia." (PMID 38399414, 2024). "Ghrelin-KO mice exhibited neither exaggerated hypoglycemia in response to recurrent hypoglycemia, nor any additional attenuation in glucagon or epinephrine compared to WT littermates." (PMID 37334290, 2023). "The findings support the continued study of utilising low-dose glucagon as a non-caloric alternative to carbohydrates for management of hypoglycaemia in individuals with type 1 diabetes." (PMID 37037948, 2023). "In normal conditions, glucagon is known to increase insulin secretion in the postprandial phase but not when it is secreted in response to hypoglycemia." (PMID 37432389, 2023). "Studies have previously shown that low doses of s.c. human glucagon can be used as an effective non-caloric alternative to carbohydrates to reverse episodes of non-severe hypoglycaemia." (PMID 37037948, 2023). "The glycemic nadir was higher in patients who received glucagon, and no episodes of hypoglycemia were reported." (PMID 36748934, 2023). "Liraglutide is known to work by stimulating the secretion of insulin whilst supressing glucagon secretion in a glucose-dependent manner and has been reported not to induce hypoglycaemia." (PMID 36773648, 2023). "Likewise, when liver glycogen levels were reduced, the glucagon and HGP responses to hypoglycemia were diminished." (PMID 37166980, 2023). "In spite of inhibiting glucagon secretion during hyperglycemia, Vildagliptin is not known to compromise glucagon counterregulatory response during hypoglycemia in T1DM." (PMID 37287751, 2023). "People with type 1 diabetes who are C-peptide positive experience less hypoglycemia than those who are negative for the protein and maintain robust glucagon responses to insulin-induced hypoglycemia." (PMID 37166980, 2023). "Both studies provided valuable insights into the efficacy and feasibility of managing non-severe hypoglycaemia using low doses of glucagon in outpatient settings." (PMID 37037948, 2023). "Hypoglycemia was noted again with an attempted transition from parenteral to enteral nutrition, so a critical sample was obtained on DOL 18 that revealed hypoketotic hypoglycemia with partial response to glucagon stimulation, suggesting possible HI." (PMID 38027095, 2023). "Two injuries required emergency department (ED) visits for severe hypoglycemia and lethargy, where the child did not receive glucagon or any oral carbohydrates at home for rescue therapy." (PMID 38571735, 2023). "The correlations of glucagon levels with HUI and GV indices in both groups were maintained after adjustment for cardiac autonomic dysfunction, suggesting that glucagon levels independently influenced hypoglycemia unawareness and GV parameters in FCPD." (PMID 35819935, 2022). "Diabetic patients have insufficient glucagon secretion during hypoglycaemia and a lack of inhibition of glucagon secretion at higher blood glucose levels resulting in postprandial hyperglucagonaemia, which contributes to the development of hyperglycaemia." (PMID 35237171, 2022). "In nondiabetic individuals, insulin secretion decreases and glucagon secretion increases to promote glycogenolysis and prevent hypoglycemia during aerobic exercise." (PMID 35345701, 2022). "Whatever the method, individuals with T1D need alternate ways to raise glucagon (that have not been impacted by their condition) to better manage hypoglycemia as long as insulin delivery stays the same." (PMID 36992764, 2022). "Chan and colleagues have demonstrated that pharmacological blockade of GABA receptors in the VMH stimulates glucagon and epinephrine secretion, without affecting blood corticosterone in response to hypoglycemia." (PMID 35619170, 2022).
Hypoglycemia (continued). "If an athlete with hypoglycemia is not awake enough to take a carbohydrate source orally, glucagon should be injected intramuscularly." (PMID 35345701, 2022). "Emergency carbohydrates can be consumed if hypoglycemia cannot be avoided by decreasing insulin delivery or increasing glucagon." (PMID 36411933, 2022). "In patients with T1DM, both vildagliptin and sitagliptin were shown to inhibit the glucagon secretion in the course of hyperglycemia, without impacting the glucagon response in the condition of hypoglycemia." (PMID 36140405, 2022). "Another study has suggested that exenatide exerts an inhibitory effect on the secretion of glucagon during either euglycemia or hyperglycemia but not affects glucagon and counter-regulatory hormones in the hypoglycemia setting in T1DM patients." (PMID 36514009, 2022). "Serum glucagon concentrations increased markedly (~16-fold) in both genotypes following insulin-induced hypoglycaemia compared to non-insulin treated mice." (PMID 35304577, 2022). "We demonstrated that epinephrine and glucagon counterregulatory responses are not attenuated by antecedent hypoglycemia under the conditions of diet-induced ketosis." (PMID 36676967, 2022). "In mice with inactivation of both Agpat5 and Cpt1a, hypoglycemia did not induce a significant reduction in glucagon secretion as compared to Agpat5flox/flox;Cpt1aflox/flox mice." (PMID 36180454, 2022). "Although falling blood glucose levels would usually lead to an increase in hepatic glucose output, this process short-circuits when glucagon responses are diminished or absent, leading to hypoglycemia during exercise." (PMID 36992764, 2022). "The “global” impact of fetal hypoglycemia on pancreas growth and function, with both insulin and glucagon concentrations being diminished, were not expected, especially since fetal liver growth and IGF1 secretion were not affected." (PMID 36293384, 2022). "This could explain why alginate DCs that did not produce physiological insulin response in vitro caused hypoglycemia in the transplanted mice in vivo: prolonged exposure to high local glucose concentrations exhausts the insulin-producing β cells and shuts down the glucagon-producing α cells." (PMID 35651551, 2022). "PACAPVMH neurons are GI and, although activating them with a stimulatory DREADD inhibits insulin (which is the first CRR to falling glucose levels), this manipulation does not release glucagon (a CRR to a deeper hypoglycemia) or affect basal glucose levels." (PMID 34265067, 2021). "Alpha cell insensitivity or irresponsiveness to paracrine signaling from the beta cell have been suggested to be involved in the lack of glucagon secretion in response to hypoglycemia." (PMID 34405569, 2021). "To note, no severe hypoglycemia (event requiring the assistance from another person for administrating carbohydrates and/or glucagon, and/or brief hospitalization) was reported, nor ketoacidosis episode over the 12-month follow-up period." (PMID 34577338, 2021). "This event leads to the blunted or even absent response of glucagon to hypoglycemia, shortly after the onset of disease in T1DM." (PMID 34572493, 2021). "Available data suggest that in type 1 diabetes the absence of glucagon secretion after hypoglycemia is irreversible." (PMID 34405569, 2021). "We also note than any potential decrease in glucagon in humans is not of significant magnitude to potentiate hypoglycaemia." (PMID 33855202, 2021). "While morphologically intact islet TH axons were observed in islets without β-cells in these T1D individuals, their medical history related to glucagon secretion or hypoglycemia episodes is not known or available." (PMID 33753784, 2021). "Last but not least, it shows the available treatments for severe hypoglycemia with a particular focus on the novel formulation of nasal glucagon." (PMID 34572493, 2021).
Hypoglycemia (continued). "Vildagliptin was reported to lower postprandial glucagon levels and improve hyperglycemia in T2DM patients, and DPP-4 inhibitors were observed to increase the abilities of alpha and beta cells to detect and respond to hypoglycemia." (PMID 34203048, 2021). "Despite the drastic reduction in plasma glucagon by pharmacological antagonism of the V1bR or genetic KO of Avpr1b, the depth of hypoglycemia was not affected." (PMID 34787082, 2021). "The ratio of insulin/glucose was 0.62, and the response of cortisol, insulin-like growth factor-1 (IGF-1), and glucagon to hypoglycemia was not significant." (PMID 34032745, 2021). "On the contrary, GIP enhances postprandial glucagon response, stimulates glucagon secretion from pancreatic a-cells during a state of hypoglycemia or euglycemia but not during hyperglycemia and stimulates glucagon secretion." (PMID 34577569, 2021). "In the event of a lack of intravenous access or acute severe hypoglycemia in unconscious patients, glucagon (intramuscular, subcutaneous injection or intranasal spray) can also be used in an emergency." (PMID 34199977, 2021). "In individuals without diabetes, hypoglycemia is initially counteracted by increased glucagon secretion and suppression of endogenous insulin release." (PMID 34444787, 2021). "In conclusion, initially high glucose levels followed by hypoglycemia with an absent glucagon response is a mechanistic sequence that contributes to postprandial hypoglycemia after TPIAT." (PMID 34067286, 2021). "In contrast to the lack of effect on glucagon, the current study shows that recurring exposure to hypoglycaemia significantly attenuated the epinephrine response to a subsequent bout of hypoglycaemia." (PMID 33855225, 2021). "Pancreatogenic diabetes is characterized by the absence of the major glucoregulatory hormones insulin and glucagon and instability and frequent hypoglycemia, and its management is crucial." (PMID 34067286, 2021). "Sympathetic innervation of islets reciprocally regulates hormone release in response to hypoglycemia by inhibition of insulin release through activation of α2-adrenergic receptors (ADRA2A) on β-cells and stimulation of glucagon secretion by activation of β2-adrenergic receptors (ADRB2) on α-cells." (PMID 33753784, 2021). "The glucagon ΔAUCs during hypoglycemia were not different over the study weeks or between the study groups." (PMID 33769710, 2021). "Previous studies in KD-fed nondiabetic mice reported an impairment in glucagon secretion in response to insulin-induced hypoglycemia." (PMID 34444787, 2021). "The derailed glucagon secretion is not confined to hypoglycemia as individuals with type 1 diabetes, as opposed to nondiabetic individuals display glucagon hypersecretion after meals, thereby potentially contributing to insulin resistance." (PMID 34405569, 2021). "In previous studies with non-diabetic rats, direct pharmacological activation of AMPK in the VMH using AICAR amplified HGP during hypoglycemia, without altering glucagon or adrenaline release." (PMID 34975743, 2021). "In contrast, hypoglycemia failed to increase circulating glucagon in all subjects with T1D, even at 60 min." (PMID 34787082, 2021). "CB-resected patients (13 ± 5 years since unilateral CB resection) show a normal counterregulatory response to hypoglycemia, indicated by similar increases in plasma catecholamines, cortisol and glucagon, compared to non-resected controls." (PMID 32698380, 2020). "Lixisenatide significantly lowered glucose and glucagon level after standardised mixed meal, without affecting counter‐regulatory response during hypoglycaemia." (PMID 32704555, 2020). "After cessation of insulin secretion in nondiabetics, glucagon is the first line of defense against hypoglycemia prior to activation of sympathetic responses." (PMID 32382023, 2020).
Hypoglycemia (continued). "While there have been studies of bihormonal actions in the liver, they have largely been studied in the context of glucagon rescue for insulin-induced hypoglycemia, which would not mimic the secretory dynamics of the 2 hormones." (PMID 32964214, 2020). "However, the ability of Prkar1a reduction to resolve fasting hypoglycemia in the Sur1-/- hyperinsulinism model exposes new possible therapeutic targets in the liver, PKA and glucagon signaling pathways in the treatment of hyperinsulinemic hypoglycemia." (PMID 32735622, 2020). "On the other hand, glucagon secretagogues, such as the TRG5 agonist ABT-777, could potentially be used in the treatment of hypoglycemia for patients with type 1 diabetes." (PMID 32382023, 2020). "The canonical view of glucagon focuses on its hepatic actions as a hypoglycemia-responsive hormone functioning in the absence of ingested mixed nutrients." (PMID 32964214, 2020). "While GLP-1 suppresses glucagon secretion at euglycemia, but not during hypoglycemia, GIP stimulates glucagon secretion at euglycemia, but not during hyperglycemia, being one of the reasons behind the apathy for GIP-based therapies for T2D." (PMID 32823659, 2020). "In an AP, however, the aim of glucagon delivery is not primarily to treat hypoglycaemia but to prevent imminent hypoglycaemia by small, and possibly repeated, doses." (PMID 32792580, 2020). "G protein-coupled receptor 119 (GPR119) agonists induce glucagon secretion during hypoglycemia but not hyperglycemia in diabetic mice." (PMID 32774668, 2020). "Using a glucagon protocol that allowed dextrose and medication optimization preceding a 24-h glucose stability period followed by a 24-h GIR reduction period, all patients ceased to have hypoglycemia, indicating efficacy of glucagon." (PMID 33013678, 2020). "GLP-1 stimulates glucose-dependant insulin secretion and inhibits glucagon release, lowering blood glucose only in the presence of insulin and not resulting in hypoglycaemia." (PMID 30865008, 2019). "IN glucagon (3 mg) has been shown to be noninferior to IM glucagon (1 mg) in treating insulin-induced hypoglycemia in adults with T1D." (PMID 31349701, 2019). "Despite this absence of hypoglycemia, plasma epinephrine and glucagon levels at that time were higher in the MTII treated diabetic mice than that in the PBS-infused diabetic mice." (PMID 30503832, 2019). "Type 1 diabetics with a normal response to glucagon however are able to recover from hypoglycemia without insulin infusion." (PMID 31829209, 2019). "GLP-1 inhibits glucagon secretion during hyperglycemia, but not when glucose levels return to euglycemia or during hypoglycemia." (PMID 31443356, 2019). "In non-diabetics, GIP stimulates glucagon secretion during hypoglycemia and potentiates insulin secretion during hyperglycemia." (PMID 31443356, 2019). "This therapy must be used with caution as the amount of insulin injected can lead to hypoglycemia if the shot of glucagon is not administered as well." (PMID 30893335, 2019). "It is known that the physiological glucagon response to insulin-induced hypoglycemia is impaired in T1DM, but not in T2DM." (PMID 31620088, 2019). "Some studies have reported that GABA acts within the VMH to modulate the magnitude of both the glucagon and epinephrine responses to hypoglycemia in nondiabetic rats." (PMID 32232085, 2018). "A previous study of GCK-MODY also reported increased glucagon (but not epinephrine) responses during experimental hypoglycemia, although hypoglycemic challenges were not matched between groups." (PMID 30146176, 2018). "Robust initiation of corrective mechanisms is particularly important for diabetic patients since even without clinical HAAF glucagon release in response to hypoglycemia is nearly absent in type 1 and advanced type 2 diabetic patients." (PMID 29593556, 2018). "In general, SGLT2i drugs do not induce hypoglycemia because they increase plasma glucagon concentrations and decrease plasma insulin concentrations." (PMID 29511288, 2018).
Hypoglycemia (continued). "Mice lacking the gene for the type 2 glucose transporter (GLUT2), a glucose transporter of particular importance for astrocytes, do not increase glucagon secretion in response to hypoglycemia as wild-type mice do." (PMID 29590557, 2018). "None of the hypoglycemia was reported as requiring other forms of carbohydrate administration, glucagon, or other resuscitative actions." (PMID 29355435, 2018). "Mice with genetic deletion of the glucose transporter type 2 (GLUT2) were not able to respond to systemic hypoglycemia with increased glucagon secretion." (PMID 29274121, 2018). "In summary, these data show that the increased glucagon counter-regulatory response to hypoglycemia in mutant I366F mice is not simply due to altered GCK activity (and insulin release/glycemia) in pancreatic β-cells." (PMID 30146176, 2018). "Selective reexpression of GLUT2 in astrocytes, but not neurons, rescued this hypoglycemia defense mechanism, suggesting that astrocytes form an obligatory component of central nervous system control of glucagon secretion." (PMID 29590557, 2018). "In keeping with this, a recent paper described mice with α-cell GCK knockout displaying increased glucagon levels, although responses to hypoglycemia were not reported." (PMID 30146176, 2018). "In agreement with effects of the glucagon-neutralizing antibodies, Gcgr null mice or normal animals administered the glucagon receptor ASOs did not develop hypoglycemia; only a mild lowering of fasted and fed plasma glucose concentrations was observed." (PMID 28323959, 2017). "The crosstalk between IGF-1 and glucagon has seldom been addressed in the literature; indeed, in the early 1990s, acute intravenous infusions of rhIGF-1 in healthy volunteers were reported to impair glucagon excretion and delay recovery after IGF-1-induced hypoglycaemia." (PMID 28881681, 2017). "Data show that intra‐VMN DAB administration to eu‐ or hypoglycemia animals did not modify circulating glucose and glucagon concentrations, despite alterations in gluco‐regulatory neurotransmitter enzyme/neuropeptide expression." (PMID 29199177, 2017). "Glucagon, rapidly released in response to an insulin-induced hypoglycemia, may serve as a common link to unify results obtained with ITT and GST as previous data suggest that glucagon is rapidly released following ITT." (PMID 26578365, 2016). "Plasma glucagon and epinephrine responses to stepped hypoglycemia after antecedent exercise without dextrose infusion were significantly lower at the 45 mg/dL glycemic level compared to after bed rest." (PMID 27597762, 2016). "Oral intake of amino acids has been reported to enhance the glucagon response to hypoglycemia and to improve some aspects of cognitive function during hypoglycemia in non-diabetic and diabetic subjects." (PMID 26521082, 2016). "Within a few years of diabetes onset, people with type 1 diabetes develop impaired counter-regulatory hormone responses, which are manifested first by decreased or absent glucagon responses to hypoglycemia." (PMID 26239457, 2015). "The biological relevance of this anorectic effect of glucagon is puzzling since glucagon increases during fasting and hypoglycemia, states that increase rather than decrease feeding." (PMID 26909312, 2015). "GLP-1 inhibits glucagon secretion from the pancreatic α-cells at fasting and elevated glucose concentrations, whereas hypoglycemia induced glucagon secretion is not inhibited - the mechanisms are not fully understood." (PMID 24400077, 2014). "Nevertheless, Chan and colleagues have clearly demonstrated that suppression of GABAergic drive in the VMH enhances the secretion of glucagon and adrenaline but not corticosterone in response to insulin-induced hypoglycemia." (PMID 24616659, 2014). "In the absence of glucagon counter-regulation, mutant mice would effectively have sufficient insulin to reduce glucose levels, thus providing a possible explanation for the hypoglycemia." (PMID 23977255, 2013).